EREG (epiregulin)
Diseases named in the same sentence as EREG in open-access papers (continued):
Sharing a sentence is not in itself a finding about the gene and the disease.
cervical cancer (continued). "The results suggested that the knockdown of EREG could induce the sensibilization of cervical cancer on cisplatin and indicated a promising synergistic therapeutic regimen of cisplatin and EREG inhibitors." (PMID 37020674, 2023). "In cervical cancer, the high expression of E2F1 was associated with the enrichment of tumor suppressor genes such as E2F signaling pathway genes (p = 0.002) and the high expression of EREG was associated with TGF-beta (p < 1E−16) signaling pathway genes." (PMID 33723286, 2021). "However, there are still rare studies investigating the role of EREG in cervical cancer." (PMID 37020674, 2023). "Moreover, EREG knockdown relieved the resistance to cisplatin in cervical cancer cells." (PMID 37020674, 2023). "Epiregulin was positively correlated with most chemokines, such as CXCL1, CXCL2, CXCL3, CXCL5, CXCL6, CXCL8, and CCL20, in most types of cancer, including cervical cancer." (PMID 37020674, 2023). "The protein–protein interaction study indicates the interacting partners of EREG, and they were EGF, TGFA, GRB2, and HRAS, and most of them regulate cervical cancer." (PMID 34439555, 2021). "Meanwhile, the number of clone formation particles in cervical cancer cells with EREG knocked down was robustly less than the negative control ones following the cisplatin treatment." (PMID 37020674, 2023). "Furthermore, the apoptosis rate of cervical cancer cells with EREG downregulated was significantly higher than the negative control ones in the treatment with cisplatin." (PMID 37020674, 2023). "Additionally, head and neck squamous cancer also shared the same immune regulation characteristics with cervical cancer, which indicated that the HPV infection might interact with EREG and together lead to cancer immune regulation dysfunction." (PMID 37020674, 2023).
colitis (7 papers, 2011 to 2024). Inflammation of the colon. "In fact, mice deficient in epiregulin are more susceptible to chemically-induced colitis but similarly induced intestinal tumors in Apc/Min model compared to WT mice." (PMID 24212947, 2011). "EREG has also been suggested that it may be involved in the paracrine regulation of colitis-associated neoplasms, because EREG stimulates the proliferation of adjacent intestinal epithelial cells leading to their development into tumor cells." (PMID 38673992, 2024). "Epiregulin is expressed during the acute phase of colitis and AR is up-regulated in the chronic period of colitis suggesting distinct roles of these ligands in mucosal repair." (PMID 24212947, 2011). "Collectively, these results suggest that the enhanced colitis-associated tumorigenesis caused by Phd2 haplodeficiency is mediated, at least in part, by activation of the STAT3 and ERK1/2 signaling pathways in tumor cells through EREG." (PMID 36509284, 2022). "In TLR4-deficient mice, neither AR nor epiregulin is expressed following mucosal injury, which is consistent with their phenotype, which includes a defective recovery from colitis." (PMID 24212947, 2011). "While evidence on EREG and AREG secretion from CAFs in response to EGFR-targeted therapy is limited, it has been shown that EREG and AREG can be overexpressed and secreted from CAFs in colitis-associated CRC as well as other cancer types to promote tumor progression." (PMID 40727266, 2024). "We and others have shown that mucosal expression of EGFR ligands, AR and epiregulin, are regulated by TLR4 signaling during colitis." (PMID 24212947, 2011). "While the precise mechanisms governing ADAM17- and EGFR-mediated protection against DSS-induced colitis remain unknown, the ErbB ligands and known ADAM17 substrates amphiregulin (AREG), epiregulin (EREG), and transforming growth factor (TGF)-α appear to be key effectors." (PMID 29312533, 2017).
COVID-19 (7 papers, 2021 to 2026). A disease caused by infection with severe acute respiratory syndrome coronavirus 2. "These subsets expressed the amphiregulin (AREG), epiregulin (EREG), and cytokine interleukin-18 (IL-18) genes and appeared to exhibit profibrogenic and proinflammatory features, suggesting that they may be potential targets for COVID-19 treatment." (PMID 36298825, 2022). "EREG has been identified as a critical mediator of IL-6/IL-17-induced upregulation of several EGF members and has been previously identified in COVID-19 as a correlate of inflammation." (PMID 37452024, 2023). "Some mediators that are modulated in bronchoalveolar lavage fluid (BALF) from patients with severe COVID-19 include the chemokines CCL2/3/4/7/8 and C-X-C motif chemokine ligand (CXCL) 1/2/6, as well as the peptide hormone epiregulin (EREG) and members of the ephrin A family (EFNA1 and EFNA5)." (PMID 35281455, 2022). "Further to these ligands, we also noted increased expression of EREG, OSM, B2M, as well as type II HLA molecules HLA-A, HLA-B, HLA-C, and HLA-E predominantly in CD4+ and CD8+ T cells and monocytes in patients with severe COVID-19." (PMID 33458558, 2021).
lung adenocarcinoma (7 papers, 2016 to 2025). A carcinoma that arises from the lung and is characterized by the presence of malignant glandular epithelial cells. "It has been revealed by other studies that the high expression of EREG in lung adenocarcinoma is detrimental to the survival of individuals." (PMID 37035196, 2023). "Among them, low expression of C12orf56, DLX5, DSC3, FEZF1, GSTA1, H2BC9, IGSF11 and high expression of EREG, CEACAM6, SLC34A2 in lung adenocarcinoma were found to predict poor prognosis for patients." (PMID 37035196, 2023). "The expression levels of AREG, BIRC3, DKK1, EREG, FOSL1, MYC, and PLAU are negatively correlated with the survival ratio, and are significantly higher in the TSPX-low lung adenocarcinoma samples, compared to TSPX-high lung adenocarcinoma samples." (PMID 39858622, 2025). "Collectively, our findings suggest that pathologic downregulation of TSPX in NSCLC, especially in lung adenocarcinoma, results in upregulation of AREG, EREG, FOSL1, MYC, and PLAU, thereby potentiating the EGFR signaling pathway and leading to the initiation and/or exacerbation of cancer development." (PMID 39858622, 2025). "Taken together, our results suggest that TSPX may suppress the development and/or progression of lung adenocarcinoma by downregulating AREG, BIRC3, DKK1, EREG, FOSL1, MYC, and PLAU, which could exacerbate lung adenocarcinoma, and upregulating the tumor suppressor CACNA2D2." (PMID 39858622, 2025).
oral cancer (6 papers, 2016 to 2025). "It was reported that overexpressed EREG promotes migration and invasion of oral cancer cells in vitro." (PMID 32929368, 2020). "It has been reported that overexpression of EREG promotes migration and invasion of oral cancer cells in vitro." (PMID 26958807, 2016). "Here, through conducting a transcriptome analysis, we demonstrated that expression of epiregulin (encoded by the EREG gene) was positively regulated by IGF2BP2, accompanied by increases in levels of several epithelial-mesenchymal transition genes and oral cancer migration." (PMID 38250159, 2024). "Collectively, these findings suggest that EREG, serving as a functional mediator of IGF2BP2-regulated EMT and cell invasion in oral cancer, may be implicated as a potential target for antimetastatic therapies." (PMID 38250159, 2024). "Many studies show that EREG expression correlated with cancer metastasis and could serve as a prognostic marker for cancers such as breast, colorectal, bladder and oral cancers." (PMID 26958807, 2016). "Epiregulin (EREG) has been identified as a potential target for antimetastatic therapy due to its role as a functional mediator of IGF2BP2-regulated EMT and cell invasion in oral cancer." (PMID 39816132, 2025). "In our study, even though the EREG level was positively correlated with fibroblast proliferation ability, colony formation and CCK8 assays revealed that modulating EREG in NFs/CAFs did not significantly alter their effects on oral cancer cell proliferation." (PMID 31234944, 2019).
liver cancer (5 papers, 2021 to 2024). An epithelial or non-epithelial malignant neoplasm that arises from the liver. "EREG has been indicated to be expressed in several HCCs, and the increase in EREG expression in liver cancer cells induces cell proliferation activity." (PMID 38673992, 2024). "In this study, EREG showed the promotion of the cell proliferation and migration/invasion of Huh7, an EGFR-expressing liver cancer cell line." (PMID 38673992, 2024). "In parallel, EREG/RAS dual knockdown leads to cycle arrest and retards liver cancer growth by regulating MAPK, PI3K-AKT, and Rb pathways." (PMID 37020674, 2023). "Dual knockdown of EREG and N-RAS induces cell cycle arrest and suppresses liver cancer cell growth through AKT, ERK, and retinoblastoma protein (Rb) pathways." (PMID 34884633, 2021). "As recent studies have focused on cellular interaction in the TME, we focused on EREG, an EGF family member that may be a mediator for LPS-induced liver cancer development, in this study." (PMID 38673992, 2024).
oral squamous cell carcinoma (5 papers, 2019 to 2024). "While the development and progression of oral squamous cell carcinoma (OSCC) are known to be driven via EGFR-HB-EGF and EGFR-EREG interactions in OSCC cells, pain is associated with EREG- or HB-EGF-mediated activation of EGFR." (PMID 38004424, 2023). "In patients with oral squamous cell carcinoma, EREG was highly expressed in CAFs compared with normal fibroblasts, and EREG-induced CAF activation promoted the EMT through IL-6 upregulation and JAK2-STAT3 pathway activation, thereby facilitating tumor growth and invasion." (PMID 38398101, 2024). "EREG is also known to be involved in EMT activation and the progression of salivary adenoid cystic carcinoma and oral squamous cell carcinoma." (PMID 38540309, 2024).
brain tumor (4 papers, 2013 to 2024). "We then confirmed the increased protein levels of Rab27b and EREG in mouse brain tumors after IR treatment by IHC staining." (PMID 33409495, 2020). "Evidence for a potential role of EREG in cell proliferation comes from data on human brain tumors." (PMID 38514807, 2024).
hepatocellular carcinoma (4 papers, 2021 to 2025). A malignant tumor that arises from hepatocytes. "It was reported that the downregulation of the EREG/Ras pathway could induce cell cycle arrest and finally trigger apoptosis in hepatoma cells." (PMID 37020674, 2023). "A study found that LPS stimulation in mice increased EREG expression in tumor tissues, which enhanced tumor angiogenesis via IL-8 signaling and promoted the migration and invasion of EGFR-positive hepatocellular carcinoma (HCC) cells." (PMID 39948481, 2025).
lung squamous cell carcinoma (4 papers, 2020 to 2024). "We have previously reported that EREG was predominantly expressed in LUAD compared with lung squamous cell carcinoma and that elevated EREG expression was an independent prognostic marker in patients with LUAD." (PMID 38398101, 2024). "Ten prognostic beneficial factors of the heterogeneous expression of lung squamous cell carcinoma genes driven by TTN mutations were screened for and DLX5, FEZF1, H2BC9, EREG, and SLC34A2 were identified as the main factors of the prognostic models." (PMID 37035196, 2023).
melanoma (4 papers, 2020 to 2025). A malignant, usually aggressive tumor composed of atypical, neoplastic melanocytes. "The cross-suppression of both AREG and EREG has also been reported to lead to the emergence of CTX resistance, which is related to the loss of cell addiction to EGFR, compensated by the hyperactivation and addiction to FGFR3 in melanoma." (PMID 36899869, 2023). "Moreover, patients with melanoma with high expression of EREG in The Cancer Genome Atlas (TCGA) cohort had a lower survival rate." (PMID 35894206, 2022).
ovarian carcinoma (4 papers, 2014 to 2025). A malignant neoplasm originating from the surface ovarian epithelium. "TSC2 acts as a tumor suppressor in a variety of cancers (e.g. oral, lung and ovarian cancers), and the upregulation of EREG has been documented in a variety of cancers (e.g. colorectal, lung, pancreatic, oral and ovarian cancers) and in TSC patients." (PMID 24748662, 2014). "Furthermore, EREG expression has been suggested to be a marker of early stages of other types of cancers, such as ovarian cancer." (PMID 26215578, 2015).
tuberculosis (4 papers, 2016 to 2020). A chronic, recurrent infection caused by the bacterium Mycobacterium tuberculosis. "We used ELISA to determine the plasma EREG level from 30 healthy controls and 50 tuberculosis patients." (PMID 30634928, 2019). "Finally, epiregulin produced by tuberculosis-infected macrophages stimulates the proliferation of surrounding normal epithelial and stromal cells." (PMID 32398031, 2020).
atherosclerosis (3 papers, 2017 to 2019). A disease characterized by the build-up of fatty material and calcium deposition in the arterial wall resulting in partial or complete occlusion of the arterial lumen. "Epiregulin contributes to inflammation, atherosclerosis and oocyte maturation by regulating vascular remodeling and stimulating cell proliferation." (PMID 28195137, 2017).
E. coli infection (3 papers, 2016 to 2024). "The results of this study indicated that miR-215 could regulate E. coli infection by targeting EREG, NIPAL1 and PTPRU genes." (PMID 32906628, 2020).
gout (3 papers, 2022 to 2024). A condition characterized by painful swelling of the joints, which is caused by deposition of urate crystals. "MiR-449a and miR-192-5p can target NLRP3 and epiregulin (EREG) to inhibit macrophage M1 polarization in gout." (PMID 36034424, 2022). "Furthermore, the overexpression of miR-192-5p could suppress the M1 macrophage polarization by targeting epiregulin (EREG) in gouty arthritis mice, leading to reduced ankle joint swelling, decreased synovial inflammatory cell infiltration and ameliorating bone erosion." (PMID 38839751, 2024).
head and neck cancer (3 papers, 2016 to 2023). A primary or metastatic malignant neoplasm affecting the head and neck. "Notably, EREG also potentially mediates the activation of the STAT3 signaling pathway in head and neck cancer." (PMID 34884633, 2021). "Finally, elevated EREG expression showed a strong correlation with poor prognosis in head and neck cancer." (PMID 26958807, 2016). "Moreover, upregulated EREG is prevalent in head and neck cancer and correlates with poor survival." (PMID 26958807, 2016).
Insulin resistance (3 papers, 2011 to 2025). Increased resistance towards insulin, that is, diminished effectiveness of insulin in reducing blood glucose levels. "Associations between epiregulin and clinical/metabolic parameters such as body mass index, insulin resistance, and androgen levels were assessed." (PMID 40638469, 2025). "Epiregulin levels showed a negative correlation with polycystic ovary syndrome status and were inversely associated with body mass index, waist circumference, Homeostatic Model Assessment Insulin Resistance, triglycerides, fasting insulin, fasting glucose, and testosterone." (PMID 40638469, 2025). "In future it has to be validated if the other most differentially regulated genes between both tissues such as: SGCD, LCE3D, EREG, NDP and CXCL9, FSTL3, PDZK1IP1 could be used as biomarkers related to insulin resistance of adipose or liver tissues respectively." (PMID 21978410, 2011).
ischemic stroke (3 papers, 2022 to 2025). A stroke disorder caused by obstruction of blood flow to the brain, due to thrombotic (local blood clot formation) or embolic (due to a blood clot or other material traveling from another site) event. "EREG and IL1B were specifically implicated in this functional category, suggesting they may modulate key receptor-mediated signaling events pertinent to ERK pathway activation in ischemic stroke." (PMID 40636523, 2025). "Using this approach, we identified a distinct gene signature—termed GSERK—including GADD45A, DUSP1, EREG, IL1B, JUN, and GADD45B as central regulatory nodes within ischemic stroke-related co-expression networks." (PMID 40636523, 2025).
psoriasis (3 papers, 2009 to 2024). An autoimmune condition characterized by red, well-delineated plaques with silvery scales that are usually on the extensor surfaces and scalp. "Accordingly, EREG-expressing DC3 have also been reported to be increased in psoriasis skin, which suggests targeting EREG may be therapeutic in other inflammatory skin conditions." (PMID 36490328, 2022). "Additionally, scRNA analysis showed that DSF might suppress EREG expression in M1 macrophages in psoriasis, which could further reduce the activation of proliferation signaling in keratinocytes through downregulation of EREG-EGFR cooperation." (PMID 38125299, 2024). "The significant induction of TNF-α increased IL-6, IL-8, EGF, HGF, TGF-α, epiregulin, and amphiregulin, but the increase in these cytokines and growth factors were not different among normal skin, uninvolved, and involved psoriasis." (PMID 20161853, 2009).
rectal cancer (3 papers, 2020 to 2025). A primary or metastatic malignant neoplasm that affects the rectum. "High EREG expression can predict a better CRT response, which is associated with an early pre‐Tx and post‐Tx tumor status in rectal cancer." (PMID 40130316, 2025). "In contrast, the epiregulin (EREG) gene was one of the top 200 genes that were co-downregulated with MUC2 (Spearman’s correlation: −0.379) and one of the favorable factors among rectal cancer patients receiving CCRT in our previous research." (PMID 34300195, 2021).
renal cell carcinoma (3 papers, 2022 to 2024). "Li and colleagues uncovered a novel lncRNA-encoded polypeptide, termed micropeptide MIAC, which weakens cancer cell growth and metastasis and accelerates apoptosis in renal cell carcinoma by inactivating the pathway of EREG/EGFR." (PMID 38351332, 2024). "In renal cell carcinoma (RCC), overexpressed micropeptide MIAC significantly reduces the capacity of cells to proliferate and migrate by binding to AQP2 and reducing EREG/EGFR expression in vitro and in vivo." (PMID 39443468, 2024).
adenoma (2 papers, 2013 to 2025). A neoplasm arising from the epithelium. "In search for differentially methylated promoters unique to a single comparative setting, hypermethylation of EREG was found unique to FAP adenomas." (PMID 40753397, 2025). "Regardless, two ligands of the mammalian EGFR pathway, amphiregulin (AREG) and epiregulin (EREG), are induced by the pro-inflammatory cytokines IL-1β and TNF-a in inflamed colonic mucosa and in adenomas and carcinomas of human colon, but not in normal colonic mucosa." (PMID 25437036, 2013).
asthma (2 papers, 2016 to 2019). "The up-regulation of epiregulin has also been shown to increase IL-8 production, which contributes to the inflammation and tissue remodeling associated with asthma, bacterial pneumonia, and chronic obstructive pulmonary disease." (PMID 31159449, 2019). "IL-6 and epiregulin are associated with a several CID, such as cancer, asthma and other pulmonary diseases, and Crohn’s disease." (PMID 31159449, 2019).
brain cancer (2 papers, 2020 to 2021). A primary or metastatic malignant neoplasm affecting the brain. "In conclusion, we found that Rab27b and EREG are co-upregulated in highly aggressive brain cancer cells, and their expression is further increased after IR treatment, leading to radioresistance in GBM." (PMID 33409495, 2020).